NR5A1 (nuclear receptor subfamily 5 group A member 1)
Description:
Transcriptional activator. Essential for sexual differentiation and formation of the primary steroidogenic tissues. Binds to the Ad4 site found in the promoter region of steroidogenic P450 genes such as CYP11A, CYP11B and CYP21B. Also regulates the AMH/Muellerian inhibiting substance gene as well as the AHCH and STAR genes. 5'-YCAAGGYC-3' and 5'-RRAGGTCA-3' are the consensus sequences for the recognition by NR5A1. The SFPQ-NONO-NR5A1 complex binds to the CYP17 promoter and regulates basal and cAMP-dependent transcriptional activity. Binds phosphatidylcholine (By similarity). Binds phospholipids with a phosphatidylinositol (PI) headgroup, in particular PI(3,4)P2 and PI(3,4,5)P3. Activated by the phosphorylation of NR5A1 by HIPK3 leading to increased steroidogenic gene expression upon cAMP signaling pathway stimulation.
Synonyms: SF-1; hSF-1; AD4BP; FTZF1; SF1; FTZ1; ELP; POF7; SPGF8; SRXX4; SRXY3
Tractability: Small molecule: a structure with a bound ligand is known; a high-quality ligand is known; it has a high-quality binding pocket; it belongs to a druggable protein family. PROTAC: UniProt records ubiquitination sites on it; ubiquitination databases record sites on it; a small molecule that binds it is known.
Target class: Nuclear hormone receptor subfamily 5; Nuclear hormone receptor subfamily 5 group A; Transcription factor; Nuclear receptor; Nuclear hormone receptor subfamily 5 group A member 1
Chemical probes: ML017, ML018, ML236, SID 7969543
Gene: Protein-coding gene on chromosome 9 (124,481,231 to 124,507,444, reverse strand). Ensembl gene ENSG00000136931.
Subcellular location: Nucleus
Subcellular location (Human Protein Atlas): Nucleoplasm; Cytosol
Pathways (Reactome):
Developmental Biology: Transcriptional regulation of pluripotent stem cells; Transcriptional regulation of testis differentiation
Gene expression (Transcription): Nuclear Receptor transcription pathway
Metabolism of proteins: SUMOylation of intracellular receptors
Gene Ontology:
Molecular function: DNA binding; DNA-binding transcription activator activity; DNA-binding transcription factor activity, RNA polymerase II-specific; enzyme binding; nuclear receptor activity; phospholipid binding; protein binding; RNA polymerase II transcription regulatory region sequence-specific DNA binding; sequence-specific DNA binding; sequence-specific double-stranded DNA binding; transcription coregulator binding; chromatin binding; RNA polymerase II cis-regulatory region sequence-specific DNA binding; DNA-binding transcription factor activity; zinc ion binding
Biological process: female gonad development; male gonad development; male sex determination; positive regulation of gene expression; positive regulation of male gonad development; positive regulation of transcription by RNA polymerase II; sex determination; hormone-mediated signaling pathway; primary sex determination; regulation of steroid biosynthetic process; regulation of transcription by RNA polymerase II; tissue development; calcineurin-mediated signaling; intracellular receptor signaling pathway; negative regulation of female gonad development; positive regulation of DNA-templated transcription; regulation of DNA-templated transcription; response to gonadotropin-releasing hormone
Cellular component: nucleoplasm; nucleus; chromatin; RNA polymerase II transcription regulator complex
Genetic constraint (gnomAD): Loss-of-function variants: 6 observed, 37.76 expected, observed/expected ratio (o/e) 0.16, 90% interval 0.086 to 0.31. The upper end of that interval is the gene's LOEUF score, 0.31, which puts it in group 1 of 6, group 1 being the genes least tolerant of losing a copy. Missense variants: 442 observed, 604.8 expected, observed/expected ratio (o/e) 0.73, 90% interval 0.68 to 0.79. Synonymous variants: 274 observed, 276 expected, observed/expected ratio (o/e) 0.99, 90% interval 0.9 to 1.1.
Homologues: Orthologues: chimpanzee NR5A1 (99% identical), macaque NR5A1 (99% identical), dog NR5A1 (95% identical), pig NR5A1 (95% identical), rabbit NR5A1 (94% identical), rat Nr5a1 (94% identical), mouse Nr5a1 (94% identical), guinea pig NR5A1 (92% identical), tropical clawed frog nr5a1 (69% identical), zebrafish nr5a1b (61% identical), zebrafish nr5a1a (56% identical), Drosophila melanogaster ftz-f1 (40% identical), and 16 more. Paralogues in human: NR5A2 (62% identical).
Diseases named in the same sentence as NR5A1 in open-access papers:
NR5A1 is named in the same sentence as 122 diseases in open-access papers, as found by Europe PMC text mining. Sharing a sentence is not in itself a finding about the gene and the disease. The quoted sentences say what the papers report.
Adrenal insufficiency (25 papers, 2007 to 2025). Insufficient production of steroid hormones (primarily cortisol) by the adrenal glands. "Variants in NR5A1 lead to a wide range of clinical presentations, including differences in sex development, infertility, and adrenal insufficiency." (PMID 41342320, 2025). "Although NR5A1 plays a role in the transcriptional regulation of key factors required for adrenal development, adrenal insufficiency is rarely associated with NR5A1 mutations." (PMID 41303802, 2025). "Recent cohort studies have further emphasized the rarity of adrenal insufficiency in patients with NR5A1 mutations, with only 5 cases identified among 197 patients." (PMID 38785542, 2024). "NR5A1 mutations causing adrenal insufficiency are rare and are likely associated with significant under-androgenicity and gonadal dysfunction in 46,XY individuals." (PMID 38785542, 2024). "Since the description of the first 46,XY DSD patient with adrenal insufficiency and a pathogenic NR5A1 variant, the spectrum of phenotypes associated with pathogenic NR5A1 variants has greatly expanded." (PMID 37185284, 2023). "The third heterozygous NR5A1 mutation associated to adrenal insufficiency and 46,XY DSD is E7X and is considered as a loss of function mutation." (PMID 28459839, 2017). "These rare observations implicate that adrenal insufficiency is associated to more severe NR5A1 mutations." (PMID 28459839, 2017). "Adrenal insufficiency associated to heterozygous and homozygous mutations in NR5A1 have been detected in three 46,XY DSD patients as well as in two 46,XX girls." (PMID 28459839, 2017). "NR5A1 mutations rarely underlie adrenal insufficiency, indicating that during human development, gonads are more vulnerable than adrenal glands to the reduced NR5A1 activity." (PMID 27833742, 2016). "The first reported 46,XX patient with a NR5A1 mutation (p.Arg255Leu) presented with isolated adrenal insufficiency, but a follow‐up description of ovarian function at postpubertal age is lacking (Biason‐Lauber and Schoenle, 2000)." (PMID 28033660, 2016). "Although occasional cases of adrenal insufficiency linked to disruptive variants in SF-1/NR5A1 were subsequently identified, it seemed likely that SF-1-associated conditions would ultimately be confined to the category of “biologically interesting, but very rare”." (PMID 38281359, 2024). "However, it has been reported that adrenal insufficiency is uncommon among individuals with NR5A1 variants." (PMID 39623453, 2024). "Although adrenal insufficiency is a rare finding in individuals with NR5A1 variants, adrenal function should be followed regularly as life-threatening adrenal insufficiency may develop later in life." (PMID 33202802, 2020). "Nevertheless, adrenal function should be followed in carriers of NR5A1 mutations, because additional factors that contribute to phenotype in the rare cases described are unknown and adrenal insufficiency may develop over time." (PMID 28459839, 2017). "Therefore, in this study we characterize novel NR5A1 mutations, one being associated with the rare phenotype of adrenal insufficiency and 46,XY DSD." (PMID 25122490, 2014). "Our data show that NR5A1 mutations can be associated with a wide spectrum of phenotypes including distal hypospadias and they highlight the need for a long-term follow up of this group of patients to see if signs of adrenal insufficiency or problems of fertility develop in later life." (PMID 22028768, 2011). "Conversely, Nr5a1+/− mouse embryos exhibit hypoplastic adrenals resulting in adrenal insufficiency and, therefore, altered stress response." (PMID 36835002, 2023).
Adrenal insufficiency (continued). "This pathogenic variant has been described in 46,XY males with similar phenotypes, but also in a 46,XY female with adrenal insufficiency, which confirms the clinical divergence of a single genotype with NR5A1 DSD." (PMID 33202802, 2020). "Previous study for heterozygous NR5A1+/− mice only revealed adrenal insufficiency during stress conditions and showed significant adrenal hyperplasia, demonstrating that normal gene dosage of SF-1 is required for mounting an adequate stress response." (PMID 30425642, 2018). "Except for five reported cases with adrenal insufficiency and some patients with mild elevated ATCH most NR5A1 mutations were described in 46,XY DSD patients with normal adrenal function at the date of examination." (PMID 28459839, 2017). "Gonadal dysgenesis and adrenal insufficiency were also present in the second reported NR5A1‐related 46,XY DSD, in a patient bearing the homozygous p.Arg92Gln mutation." (PMID 28033660, 2016). "After this first report, the study of several cohorts of individuals with 46,XY DSD has shown that adrenal insufficiency is a rare finding in patients with NR5A1 defects." (PMID 28033660, 2016). "Human NR5A1/SF-1 mutations cause 46,XY disorder of sex development (DSD) with broad phenotypic variability, and rarely cause adrenal insufficiency although SF-1 is an important transcription factor for many genes involved in steroidogenesis." (PMID 25122490, 2014). "In 2000, Biason-Lauber and Schoenle described a de novo heterozygous NR5A1 change in a girl who had presented at 14 months of age with primary adrenal insufficiency and seizures." (PMID 21078366, 2011). "Human NR5A1 mutations were first reported in association with 46,XY DSD and adrenal insufficiency and in a 46,XX girl with adrenal insufficiency." (PMID 22028768, 2011). "Phenotypes ranged from ambiguous genitalia and cryptorchidism to complete gonadal dysgenesis, often without adrenal insufficiency—highlighting the variable penetrance and expressivity of NR5A1 mutations." (PMID 41220431, 2025). "Of note, other conditions related to the NR5A1 variant were absent in our cohort, including adrenal insufficiency, which remains rare despite its early description in NR5A1 patients." (PMID 41342320, 2025). "As adrenal insufficiency is described in some but not all patients with NR5A1 mutations, adrenal testing is recommended." (PMID 37185284, 2023). "However, because systemic Nr5a1 knockout mice die in the neonatal period due to adrenal insufficiency, tissue-specific functions of NR5A1 are not well understood." (PMID 36613635, 2022). "The clinical differentials of sex reversal with adrenal insufficiency include P450scc deficiency due to mutations in CYP11A1 gene, Smith-Lemli-Opitz syndrome (DHCR7 gene), NR5A1 (SF1) mutation-related sex reversal, CYP17 and 3-beta hydroxysteroid dehydrogenase deficiency (HSD3B2 gene)." (PMID 23748066, 2013). "While mutation-positive human patients showed no signs of adrenal insufficiency, the mutation may still impair NR5A1 function in human adrenal glands because NR5A1 haploinsufficiency usually permits normal adrenal function in humans." (PMID 27833742, 2016). "A human variation in NR5A1 was first detected in a 46,XY DSD individual with complete gonadal dysgenesis combined with adrenal insufficiency, and was mimicking the phenotype of the Sf1 knockout (KO) mouse." (PMID 33202802, 2020). "Patient 1 (family 1), a boy with adrenal insufficiency and 46,XY DSD harbored compound heterozygote novel c.19G>T and c.887C>T variations in the NR5A1 gene coding for Glu7Stop in the DNA binding domain and Thr296Met in the ligand binding domain." (PMID 25122490, 2014).
Infertility (23 papers, 2009 to 2025). "A total of 26 distinct NR5A1 gene variants were identified among the 23 infertile Senegalese men analyzed." (PMID 41386844, 2025). "This exploratory pilot study aimed to identify and characterize NR5A1 variants in infertile Senegalese men and to assess genotype–phenotype correlations." (PMID 41386844, 2025). "Conversely, NR5A1 mutations result in a broad spectrum of DSDs and abnormalities of puberty, such as hypergonadotropic hypogonadism and infertility." (PMID 38785542, 2024). "Hypogonadism and infertility are other clinical phenotypes of patients with DSDs due to NR5A1 mutation." (PMID 38785542, 2024). "Mutations in NR5A1 have been observed in men with infertility or hypospadias as well as in 46,XY individuals with ambiguous genitalia or anorchia, but also in 46,XY girls with primary amenorrhea with and without Müllerian structures." (PMID 28459839, 2017). "•Identified 26 NR5A1 variants in 23 infertile Senegalese men." (PMID 41386844, 2025). "NR5A1 gene mutations could be mainly associated with amenorrhea, ovarian failure, hypogonadism, and infertility during puberty." (PMID 38785542, 2024). "In 46,XY individuals with a pathogenic variant in the NR5A1 gene a variable phenotype ranging from mild to severe is seen, including adrenal failure, testis dysgenesis, androgen synthesis defects, hypospadias and anorchia with microphallus and infertility." (PMID 37185284, 2023). "The present review confirms that NR5A1 gene mutations can manifest with a wide phenotypic spectrum, ranging from complete gonadal dysgenesis with female external genitalia to milder degrees of undervirilization or even apparently normal male genitalia with later infertility." (PMID 41303802, 2025). "We conducted a cross-sectional study in 23 infertile Senegalese men, and exons 2 –7 of NR5A1 were sequenced using the Sanger method." (PMID 41386844, 2025). "Pituitary-specific knockout of Nr5a1 in mice resulted in depleted lhb and fshb levels and infertility." (PMID 39499852, 2024). "Three studies report infertility in 3 males, all of whom were carriers of the pathogenic variants reported (PSMC3IP, NR5A1, and STAG3 variants)." (PMID 38737775, 2023). "Mutations in NR5A1 have been reported as a frequent cause of 46,XY disorders of sex development (DSD) associated to a broad phenotypic spectrum ranging from infertility, ambiguous genitalia, anorchia to gonadal dygenesis and female genitalia." (PMID 28459839, 2017). "In 46,XX individuals, NR5A1 mutations are a rare genetic cause of POI, manifesting as primary or secondary amenorrhea, infertility, hypoestrogenism, and elevated gonadotropin levels." (PMID 28033660, 2016). "The men who harbored NR5A1 changes had more severe forms of infertility (azoospermia, severe oligozoospermia) and in several cases low testosterone and elevated gonadotropins were found." (PMID 21078366, 2011). "While rare deleterious NR5A1/SF-1 variants have been identified in individuals with various differences of sex development (DSD), primary ovarian insufficiency, and infertility, their impact on the general population remains unclear." (PMID 39479520, 2024). "NR5A1 alterations are associated with a large spectrum of clinical phenotypes, from isolated infertility in male patients to 46,XY sex reversal, without adrenal failure in most patients." (PMID 37855374, 2023). "New variations of gene NR5A1 have been shown to influence the decline of the ovarian reserve, causing primary ovarian insufficiency, which can cause primary ovarian insufficiency (POI) and infertility." (PMID 34362406, 2021). "However, autosomal dominant monogenic mutations can also precipitate a state of infertility including SYCP3 (Synaptonemal complex protein 3), NR5A1 (nuclear receptor subfamily 5 group A member 1) and the WT1 (Wilms' tumor 1) gene." (PMID 33101214, 2020). "Abnormalities affecting Nr5a1 expression lead to hypogonadotropic hypogonadism and infertility." (PMID 31391075, 2019).
Infertility (continued). "When samples from the control infertile group (group 1B) were compared with samples from the OE infertile group (group 2B), higher levels of the NR5A1 (P < 0.0001), STAR (P < 0.0001), CYP19A (P < 0.01), ESR1 (P < 0.05) and ESR2 (P < 0.001) transcripts were detected in group 1B than in group 2B." (PMID 31878927, 2019). "To investigate whether mutations in SOX8, like NR5A1,could also contribute to a wider spectrum of male and female infertility, we sequenced thecoding region of SOX8 in 427 men and women with infertility." (PMID 29373757, 2018). "Today more than 100 different mutations in the NR5A1 gene are listed in the Human Gene Mutation Database (HGMD) and have been described mostly associated with 46,XY DSD, but also associated with hypospadias, cryptorchidism, infertility or anorchia." (PMID 28459839, 2017). "Other causes of premature menopause or infertility were not excluded, as only one mother shares the NR5A1 mutation with her son." (PMID 27899089, 2016). "Among the 23 infertile men, four patients (IDs 10, 11, 12 and15) did not carry any NR5A1 variant." (PMID 41386844, 2025). "But, NR5A1/SF-1 variants can also be identified in individuals without DSD, including healthy carriers, infertile men, or women with primary ovarian insufficiency (POI)." (PMID 39479520, 2024). "The segregation of pathogenic loss of function variants in PSMC3IP, NR5A1, and STAG3 with POI in 13 female carriers and non-obstructive azoospermia (NOA) in three male carriers in the studied pedigrees suggested a significant role of these variants in infertility in both genders." (PMID 38737775, 2023).